EGFR (epidermal growth factor receptor)
Diseases named in the same sentence as EGFR in open-access papers (continued):
Sharing a sentence is not in itself a finding about the gene and the disease.
tumor (continued). "Together, these data suggest EGFR as a potential therapeutic target for patients afflicted with neuropathic pain that in the treatment of cancer-related neuropathic pain may be at least partly distinct from the effect of EGFR therapies on the tumor itself." (PMID 34054523, 2021). "In addition, EGFR is expressed on endothelial cells of the tumor microenvironment, where it contributes to angiogenesis, proliferation and metastasis through stimulation of vascular endothelial and fibroblast growth factors, and interleukin-8 4,63." (PMID 34522225, 2021). "Interestingly, no change in expression levels of mesenchymal-associated genes VIM, EGFR, FOSL1 and FN1 was observed between CTCs and their primary tumours in any of the models." (PMID 34206049, 2021). "Therefore, tumor cells begin to harbor resistance to tyrosine kinase inhibitors and anti‐EGFR monoclonal antibodies by modulating MEK and ERK signaling." (PMID 34101386, 2021). "To investigate if and which T cell immunotherapy most effectively curbs RMS tumor growth in vivo, we next performed a side-by-side comparison of EGFR CAR T cells, BiTEs, and APECs to assess differences in killing of RMS cells engrafted into rag2Δ/Δ, il2rga−/− zebrafish." (PMID 34415995, 2021). "In light of our results, it could be speculated that the reported abundance of EGFR (Erb-B1) on endothelial cells of tumor vessels could depend on an enrichment mediated by the release of Exos by the malignant cells." (PMID 33237352, 2021). "However, it is in marked contrast to the current circulating tumor DNA (ctDNA) literature which suggests that pre-existing or de novo generated RAS and de novo EGFR mutations are the primary cause of SR development in up to 96% of CRCs." (PMID 34271981, 2021). "Furthermore, they established a direct positive trend between EGFR expression and the grade of the tumour." (PMID 34943184, 2021). "Tumor cells could be completely blocked when ALOC-EO was added to cells treated with anti-EGFR or siRNA against EGFR." (PMID 34360915, 2021). "Results of the molecular analysis of the tumor were negative for epidermal growth factor receptor (EGFR) genotype mutations, ALK and ROS 1 rearrangement, and PDL-1 protein expression." (PMID 33832072, 2021). "All tumor markers except EGFR revealed strong immunopositivity." (PMID 33313992, 2021). "Activation of the kinase AXL induces EGFR-TKI resistance associated with the mesenchymal phenotype, and the dual blockade of MEK and AXL overcomes EMT-mediated drug resistance and synergistically suppresses tumor growth in KRAS-mutated lung cancer cells." (PMID 34885068, 2021). "Thus, we didn’t think that tumor stage and tumor size were indirectly related with the acquired EGFR-TKIs resistance according to the present data." (PMID 33441708, 2021). "Epidermal growth factor receptor (EGFR) is often over-expressed in tumor cells." (PMID 33738260, 2021). "In some patients, when radiotherapy and EGFR-TKIs are started simultaneously, the purposes of both increasing the dose to the primary tumour and protecting normal tissues from radiation injury cannot be achieved because of the primary tumour volume." (PMID 34631535, 2021). "EGFRvIII is expressed in approximately one-third of GBMs and is more tumour-specific than EGFR." (PMID 34868634, 2021). "In vivo and in vitro experiments on NSCLC and TNBC showed that EGFR/Notch-bispecific mAbs exhibit potent anti-tumor effects, especially decreasing the abundance of CSCs, which limits tumor resistance to EGFR-TKIs and has potential value for clinical applications." (PMID 34195229, 2021). "Furthermore, the significant intra-tumor heterogeneity of epidermal growth factor receptor (EGFR) activity influences drug function." (PMID 34138374, 2021).
tumor (continued). "Protein levels of HER signaling pathway members and STAT3 in tumor tissues showed a synergistic decrease in EGFR, HER2 and STAT3, and the activation of HER3 and downstream signaling effectors Akt and ERK was abrogated by joint treatment in both SKBR3 and SKBR3-L xenografts." (PMID 34290605, 2021). "In one word, the photoacoustic imaging results showed that ZEGFR:1907-Ag2S QDs could detect EGFR-positive tumor cell lines perfectly." (PMID 34322025, 2021). "EGFR/INSIG-1/SREBP-1 signaling is critical for tumor growth, maintenance, and metastasis." (PMID 34518524, 2021). "This series of studies aimed to identify a potent compound against EGFR-driven tumor." (PMID 34925034, 2021). "EGFR variant allelic frequency was driven by copy number status but did not correlate with the visually estimated tumor cellularity in our data." (PMID 33869038, 2021). "This would suggest that reducing ZDHHC20 in vivo should have a negative effect on either tumour growth or progression, although it is not apparent from these studies if these effects stem from a loss of EGFR palmitoylation by DHHC20." (PMID 34610265, 2021). "Similarly, for 90% of the patients from the ID-MUT study, the EGFR genotyping result was determined to be 15–16 cd (10–11 wd) after tumor sampling with the IdyllaTM method, against 23–24 cd (19–20 wd) for the NGS method." (PMID 34898548, 2021). "One patient (LAT026) in Cohort 2 with a high calculated tumor burden of 148 cm3 did not have detectable EGFR mutations." (PMID 34283064, 2021). "Intriguingly, tumor IGF1R expression is associated with lymphatic invasion and predicts shorter progression-free survival in EGFR-mutant but not EGFR–wild type NSCLC, suggesting a unique interplay between EGFR and IGF1R pathways in this type of malignancy." (PMID 32292420, 2020). "Less than 10% of the tumor cells showed weak expression of EGFR." (PMID 32979929, 2020). "New targeted therapies for mutations in EGFR, ALK (anaplastic lymphoma kinase), immunotherapy PD-1 (programmed death-1) receptor, and programmed death ligand 1 (PDL-1) have shown promising results in both primary tumor and BM but require further studies." (PMID 31900168, 2020). "Nevertheless, we obtained samples from the same primary tumor site from 3 treatment time points from a patient (TH226) whose tumor contained a standard EGFR exon 19 deletion oncogenic mutation and was treated with the EGFR inhibitor osimertinib." (PMID 32822576, 2020). "Furthermore, T47D and SKOV-3 cells (low EGFR) were included in PDAC (MIA PaCa-2) and HNSCC (SCC-9) 3D nodules to recapitulate heterogeneous tumor cell subpopulations that would evade EGFR-targeted Cet-PINs." (PMID 32726945, 2020). "As HLA-I upregulation is associated with tumor-specific CD8+ mediated immune response, these cells may also lead into sPD-1 secretion after anti-EGFR treatment." (PMID 33329567, 2020). "Besides staining within the tumor, normal squamous epithelium and skin adnexa also expressed EGFR with a similar intensity found in the tumor." (PMID 32516897, 2020). "The tumor inhibitory rate of rLZ-8 was correlative with the EGFR expression." (PMID 32079107, 2020). "Another study demonstrated that TNF-α increased EGFR expression in tumor cells." (PMID 32974124, 2020). "Finally, we focused on patient 21, with a pT3N0 intestinal histologic subtype tumor arising from the gastric antrum characterized by gains of EGFR, MYC (OMIM 190080) KRAS, MET, and PIK3CA by OncoScan (eFigure 4C in the Supplement)." (PMID 32338752, 2020).
tumor (continued). "As the EGFR localized in these organelles can display novel functions and may regulate the response of a tumor to therapy, it is important to characterize the novel functions of EGFR in these organelles." (PMID 32321917, 2020). "This study shows that the hyperspectral signal may be used to detect a residual tumor in post-surgical specimens of cutaneous SCC stained with anti-EGFR conjugated GNPs." (PMID 31963462, 2020). "Despite only subsets of EGFR mutant tumours displayed responses to immune checkpoint blockade, the understanding of the underlying mechanisms in relation to EGFR and immune checkpoint expression may provide new attractive therapeutic paths." (PMID 33302515, 2020). "The stimulation of the EGFR pathway also promotes tumor cell migration, adhesion, and metastasis." (PMID 32596278, 2020). "Our study showed that HD-SB inhibited tumor growth both in vitro and in vivo, which might be related with apoptosis induction via the EGFR/PPARγ/PI3K/AKT pathway." (PMID 32265701, 2020). "Remarkably, activation of EGFR not only promotes tumor cell escape from immune surveillance, but it also inhibits the activity of cytotoxic T lymphocytes (CTLs) through different mechanisms such as the increased lactate excretion, the activation of T regs and the decrease of MHC I and II expression." (PMID 32024070, 2020). "Although neither Spred1 nor Nav3 mutations affected tumor cell sensitivity to EGFR inhibition with afatinib, loss of Spred1 or Nav3 increased sensitivity of EGFRvIII-tumor cells to MEK inhibitor treatment with trametinib." (PMID 32727536, 2020). "Besides, the antibody restores MHC-I expression on tumor cells, hindering one of the EGFR immune-escape ways." (PMID 32537431, 2020). "Over-expression of EGFR in this tumor was shown by immunocytochemistry." (PMID 35047884, 2020). "Tumor tissues had increased levels of EGFR and related growth factors at early stages." (PMID 32795296, 2020). "Regarding EGFR mutations, the NIC in the AP and VP and λHU in the VP were higher in tumours with EGFR mutations than in those without EGFR mutations, and the NIC in the VP was an independent factor influencing EGFR mutation." (PMID 32103127, 2020). "Nimotuzumab restores MHC-I expression on tumor cells, hindering one of the EGFR immune-escape ways." (PMID 32537431, 2020). "In this study, we constructed a recombinant adenovirus expressing EGFR-targeting artificial microRNA and active revCASP3 (Ad-EC), under the control of tumor-specific SLPI promoter, and evaluated its inhibitory effect on HEP-2 cancer cells both in vitro and in vivo." (PMID 32745124, 2020). "Among patients with a tumor proportion score of ≥50% for PD-L1 and lacking sensitizing EGFR or ALK mutations, pembrolizumab has replaced cytotoxic chemotherapy as the first-line treatment of choice." (PMID 33101670, 2020). "IGF-1R exhibits crosstalk with EGFR and mediates tumour resistance to EGFR inhibitors, and a phase II clinical trial (NCT00769483) showed that MK-0646, an IGF-1R antagonist, synergistically improved OS when applied with gemcitabine (10.4 months vs 5.7 months, P value = 0.02)." (PMID 33008426, 2020). "The objectives of this study were: 1) to compare EGFR and KRAS mutation status between plasma and tumor tissue in surgically resected TKI-naïve NSCLC; 2) to compare histopathological features between ctDNA shedding and non-shedding tumors; and 3) to evaluate parameters predicting ctDNA shedding." (PMID 32196518, 2020). "Molecular testing (circulating tumor ctDNA by high-throughput next-generation sequencing) revealed no EGFR mutations or ALK rearrangements." (PMID 33285759, 2020). "The dimerization interface of EGFRvIII, whether in the context of a homodimer with a partner EGFRvIII or as a heterodimer with wild-type (over-expressed) EGFR, is a possible site of a tumor-specific epitope." (PMID 33187135, 2020).
tumor (continued). "EGFR expression can be detected in the cell membrane and cytoplasm of tumour cells." (PMID 33123565, 2020). "Cetuximab eradicates tumor cells partially by downregulating the EGFR expression." (PMID 33028895, 2020). "In this study, we first investigated the possible effects of EGFR-TKIs on tumour lymphangiogenesis." (PMID 31892990, 2020). "In patients treated with EGFR inhibitors, EGFR expression was diminished both in the tumor as well as skin samples, which demonstrates the parallel and simultaneous biological effects of these drugs, making it possible to determine the stage of blockade of EGFR with a skin biopsy analysis." (PMID 33015988, 2020). "Studies have shown that IGFBP-3 participates in the repair of DSB damage through NHEJ, responds to DNA-destructive chemotherapy, and forms a nuclear complex with EGFR and DNA-PKCs, promotes the stability of tumor cell genome and leads to the migration and invasion of tumor cells." (PMID 32653017, 2020). "Results showed three EGFR mutated tumors (13% of lung AD cases), five K-RAS mutated tumors (two patients; 8.7% of AD cases and three patients; 20% of SCC cases), and one N-RAS mutated tumor (6.7% of SCC cases)." (PMID 32971741, 2020). "Moreover, blockade of HB-EGF–EGFR signaling, by an anti-HB-EGF neutralizing antibody or the EGFR inhibitor erlotinib, limited the angiogenic potential of bone marrow endothelial cells and hampered tumor growth in an MM xenograft mouse model." (PMID 31936715, 2020). "Note that a meta-analysis performed on mCRC suggests that patients with left-sided RAS wt tumours achieve a benefit from being treated with chemotherapy plus EGFR antibody therapy, while our study population received cetuximab-based treatment combined, or not, with chemotherapy." (PMID 33347495, 2020). "For example, as already mentioned, EGFR activation by EGF binding can induce PD-L1 expression on tumor cells; however, EGFR-mutant NSCLCs tend to have lower PD-L1 expression levels compared to EGFR-wild type tumors as a result of the interaction between tumor cells and the immune TME." (PMID 33114576, 2020). "Generally, tumor cells are accompanied by high expression of EGFR under hypoxic conditions." (PMID 33148251, 2020). "Interestingly, the epidermal growth factor receptor (EGFR) has been shown to play a key role in tumor cell escape from immune surveillance, and in cytotoxic T lymphocyte inhibition." (PMID 32024070, 2020). "The HER2 and EGFR over expressions had an important role in the early stages of tumor progression." (PMID 32795296, 2020). "The PI3K/AKT pathway is frequently activated in HNSCC, and may constitute a source of tumor escape during EGFR targeting." (PMID 32296588, 2020). "Second, in five of the 27 patients, the tumor PD-L1 expression was evaluated using tissue samples obtained after the initiation of EGFR-TKI treatment, and there are reports to suggest that the tumor PD-L1 status could change during treatment." (PMID 33255696, 2020). "In addition, 58 (14.1%) patients were administered EGFR TKIs because of tumor recurrence after definitive surgery." (PMID 33014788, 2020). "After dissection, 33% of the samples that were negative for EGFR mutation with a tumour content ratio < 10% were corrected to EGFR positive, although only 14% recovery was observed in the samples with negative EGFR samples with a tumour content more than 10%." (PMID 32028905, 2020).
tumor (continued). "Specifically, whereas panitumumab (anti-epidermal growth factor receptor (EGFR) IgG2) was inactive in triggering ADCC by mononuclear cells, it induced tumor cytotoxicity when using neutrophils as effector cells to a similar extend as zalutumumab (anti-EGFR IgG1)." (PMID 33105656, 2020). "A putative relation between EGFR/KRAS mutation and the promoter methylation of CDH1, CDKN2Ap16, RASSF1A, TERT, and WT1 could influence tumor progression and therapy response." (PMID 32605217, 2020). "EGFR plays an important role in the proliferation, growth, repair and survival of tumor cells." (PMID 32776462, 2020). "In addition, the total EGFR was sparser in Area R than in Area P, suggesting a higher EGFR suppression in the stroma-rich tumor area." (PMID 33028895, 2020). "In this model, the anti-tumor effect of the bispecific trimerbody was dependent on human EGFR expression, but the potential toxicity profile was dictated by the endogenous mouse EGFR." (PMID 33488625, 2020). "The effects of α5-nAChR on cell proliferation, migration, and EMT can be witnessed in both EGFR wild-type (A549) and EGFR mutant (HCC827 and H1975) cell lines; the animal experiment using HCC827 also proved that α5-nAChR can affect the tumor growth in EGFR-mutant cells." (PMID 32957649, 2020). "Importantly, we show that tumours having the most common mechanisms of clinically-observed resistance to high dose standard of care EGFR inhibitors still respond to MLD therapy." (PMID 32572029, 2020). "In addition, sEVs displaying EGFR or HER2 have also been found to be involved in the recruitment and differentiation of tumour-associated macrophages (TAMs)." (PMID 33228060, 2020). "If tumor cells carry both EGFR and ALK alterations, a combination of both TKIs may be a potentially reasonable choice." (PMID 33363040, 2020). "The results revealed good tumor-targeting effect of the recombinant adenovirus Ad-EC with the tumor specific promoter modulated expression of revCASP3 and artificial microRNA targeting EGFR." (PMID 32745124, 2020). "Specifically, EVs EGFR, as a special membrane surface marker, has a promoting effect in tumour progression and metastasis, and targeting EGFR may be therefore a promising strategy for improving the therapeutic outcome and prognosis of cancer patients." (PMID 33304472, 2020). "Regarding other clinicopathological characteristics of LADC, the distribution frequency of AURKA SNP rs6024836 was numerically higher in the mutated EGFR group with a lower tumor T status, absence of lymph node involvement, and negative distant metastasis." (PMID 33050100, 2020). "Adnectin monobodies were introduced into CAR-T systems to target tumours overexpressing VEGFR2 or EGFR, and through reducing affinity to EGFR the CAR-T cells were engineered to only reach effective concentrations at tumour cells which drastically over-express the target receptor." (PMID 32143310, 2020). "Similarly, anti-EGFR Nb 99mTc-7C12 was able to monitor the response to tyrosine kinase inhibitor Erlotinib in an A431-tumor xenograft mouse model, using pinhole SPECT/micro-CT." (PMID 33353213, 2020). "The inhibition of tumor growth by the two anti-EGFR sdAbs was comparable with DDP." (PMID 33023595, 2020). "It is possible, however, that multiple mutation events resulting in EGFR and PDGFRA amplification in cells could be occurring in an evolving tumour and it may be more appropriate to model such single cell events in a micro- or meso-scopic setting." (PMID 33120534, 2020). "Interestingly, two patients who initially responded to TKI demonstrated a change in the LAMP1 distribution at the time of progression of the disease, when the tumor stopped responding to EGFR TKI." (PMID 32194831, 2020). "In addition, the percentages reported largely depend on tumour histology, especially for ALK and EGFR mutations." (PMID 32236766, 2020).